EREG (epiregulin)
Diseases named in the same sentence as EREG in open-access papers (continued):
Sharing a sentence is not in itself a finding about the gene and the disease.
Stroke (1 paper, 2021). Sudden impairment of blood flow to a part of the brain due to occlusion or rupture of an artery to the brain. "Calcium signaling pathway-related genes (AC079305.10, BCL10, BCL2A1, BRE-AS1, DYNLL2, EREG, and PTGS2) are related to apoptosis after stroke, whereas posttranscriptional regulation of BCL2A1 may be possibly associated with IS." (PMID 34987704, 2021).
tendinopathy (1 paper, 2019). "Given the role in cell proliferation, angiogenesis and fibrosis upon inflammation, and considering that they are hallmarks of tendinopathy, targeting the CX3CL1/CX3CR1/EREG axis could potentially open up new vistas in tendinopathy therapy." (PMID 31744815, 2019).
thymic carcinoma (1 paper, 2021). Thymic carcinoma (TC) is a type of thymic epithelial neoplasm characterized by a high malignant potential. "Immunohistochemical (IHC) analysis revealed a high expression (91.7%) of the EREG protein in thymic carcinomas, indicating that EREG is commonly expressed in thymic cancer tissues." (PMID 34884633, 2021).
tumor (163 papers, 2008 to 2026). "Previous studies have elucidated the involvement of EREG in the pro-tumoral phenotype of the tumor microenvironment in which cancer-associated fibroblasts (CAFs) are the major source of EREG." (PMID 38398101, 2024). "The tumor stemness indicators RNAss, ENHss, DMPss, DNAss, EREG-METHss, and EREG-EXPss were also associated with S100A7 expression." (PMID 38499391, 2024). "EREG is overexpressed in many human cancers and has been implicated in tumor progression (e.g. resistance to apoptosis) and metastasis." (PMID 38096046, 2024). "ART1's associations with key markers of tumor proliferation and growth processes, including DNAss, RNAss, EREG.EXPss, EREG-METHss, DMPss, and ENHss, underscore its intricate involvement in tumorigenesis and tumor progression." (PMID 38911388, 2024). "NMU and EREG encode for Neuromedin U and Epiregulin, respectively, both of which are involved in tumor invasion and progression." (PMID 36868311, 2023). "In the present study, PCDH10 overexpression significantly decreased the expression of genes associated with tumor progression and metastasis, including EREG, MMP1, MMP9, TGFB1, RASA4, and CXCL8, in GC cells." (PMID 37147733, 2023). "p38, STAT3, ERK1/2, and JNK phosphorylation were generally higher in ATF4-deficient tumours, which expressed more EREG but less FGF21 mRNA." (PMID 36996941, 2023). "High expression of EREG was associated with tumor stage, metastasis and survival in human cancer patients." (PMID 36733484, 2023). "Further, increased expression of EREG in cancer-associated fibroblasts also deserves attention, as it correlates with higher tumor stage, enhanced invasiveness and shorter overall survival of cancer patients." (PMID 36202915, 2022). "The upregulated genes, including WNT11, HAPLN1, FGF10, BBOX1, CXADR, NDP, and EREG are associated with tumor proliferation, migration, and cancer stemness." (PMID 35954313, 2022). "Low AREG and EREG mRNA levels in mCRC tumor tissues are associated with BRAF mutations and correlated with shorter OS in patients with cancer-receiving oxaliplatin/fluoropyrimidine and bevacizumab as combinational treatment." (PMID 34884633, 2021). "Depletion of EREG diminished the formation of lung tumors in a primary two-stage mouse model, and exposure to 3-methylcholanthrene and butylated hydroxytoluene caused tumor initiation and progression, respectively." (PMID 34884633, 2021). "EREG promotes tumor cell survival, and previous studies have demonstrated that EREG is linked to pulmonary metastasis." (PMID 27995036, 2016). "Despite the morphologic similarity based on H&E staining, immunoblot analysis of tumor lysates demonstrated that loss of EREG was associated with decreased phosphorylation of EGFR." (PMID 26215578, 2015). "This is in accordance with previous data suggesting that PR isoforms expression correlated negatively with other members of the same gene family associated with tumor aggressiveness such as EREG and TGF alpha." (PMID 26474308, 2015). "Reduced EREG expression in MCF10DCIS cells led to decreased tumor growth in vivo, which was associated with reduced cell survival." (PMID 26215578, 2015). "Regarding objective tumour response to any line of cetuximab-based therapy, tumoural AREG and EREG mRNA expression levels were associated with tumour shrinkage as continuous variables." (PMID 23374602, 2013). "TTP and OS to the ≥2nd line cetuximab-containing treatment according to KRAS, BRAF, PIK3CA mutations status, PTEN protein expression, AREG and EREG mRNA expression and grade of skin rash in the KRAS WT patients′ population." (PMID 21283802, 2011). "EREG was mainly expressed by (tumor-associated) macrophages/microglia." (PMID 39959305, 2025). "In most tumor entities, EREG is upregulated and associated with metastasis and poor prognosis." (PMID 36994208, 2023). "Notably, elevated EREG expression is implicated in the activation of inflammation during the early tumor initiation described in the next section." (PMID 34884633, 2021).
tumor (continued). "Low expression levels of AREG and EREG associated with KRAS mutations might indicate a tumor that is less dependent on EGFR and is therefore particularly prone to developing resistance to anti-EGFR MoAbs." (PMID 31771279, 2019). "Similarly, high tumor EREG mRNA expression was found to be associated with improved prognosis upon Cetuximab treatment, in a randomized phase III clinical trial." (PMID 31181806, 2019). "Based on these data, promoter DNA methylation may be the main regulatory mechanism of AREG/EREG expression, which may explain, at least in part, the association between right-sided tumor location, CIMP-status and anti-EGFR treatment response in mCRC." (PMID 34532592, 2018). "Similarly, elevated EREG expression in NSCLC is associated with aggressive tumor phenotypes and unfavourable prognosis." (PMID 28415726, 2017). "Elevated EREG expression in the tumor microenvironment, particularly from fibroblasts and macrophages, activates EGFR signaling through autocrine and paracrine loops, enhancing fibroblast migration and contributing to therapeutic resistance in CC." (PMID 40055606, 2025). "Previous studies have demonstrated that the LPS-mediated upregulation of epiregulin contributes to tumor neovascularization via IL-8 signaling in HCC." (PMID 40724957, 2025). "In treatment-naive samples, Mono_EREG exhibited high expression of CCL family genes (CCL3L3, CCL20), EREG, and BCL2A1, which are associated with tumor progression, suggesting functional impairment." (PMID 40725006, 2025). "Among members of the EGF family, only the EREG expression in tumor tissue showed a higher expression in the LPS-treated group than in the negative control." (PMID 38673992, 2024). "Among these, M11 exhibited high expression of metallothionein, and M4 expressed EREG, which promotes tumour growth." (PMID 39656344, 2024). "Our results unveil a tumor-promotive role of IGF2BP2 in OSCC progression through the induction of EREG expression and cancer cell invasion." (PMID 38250159, 2024). "They reported that macrophages in the tumor microenvironment secrete EREG, which in turn leads to the formation of the EGFR/ErbB2 heterodimer and induces resistance to EGFR-TKIs through the activation of the PI3K/AKT pathway." (PMID 38398101, 2024). "EREG is poorly expressed in most normal tissues, but overexpressed EREG triggers its downstream signaling pathway and promotes tumor progression while binding to EGFR." (PMID 38318160, 2024). "LX-2 detected by alpha-smooth muscle actin (αSMA) staining showed a higher expression level of EREG in tumor tissue in the LPS-treated group than that in the PBS group, suggesting that activated HSCs are the major source of EREG in these xenografted tumors." (PMID 38673992, 2024). "For CD14+ monocytes, the VEGFA/PGF-VEGFR1 axes play a significant role in tumor angiogenesis, and the EREG/AREG-EGFR communications serve as a critical factor in tumor proliferation in several solid human cancers." (PMID 38600248, 2024). "In the tumor tissue stimulated with LPS, the EREG expression significantly increased compared with that in negative controls, as seen in previous studies." (PMID 38673992, 2024). "Recent studies have elucidated the roles of EREG in a tumor microenvironment, including the epithelial–mesenchymal transition, angiogenesis, immune evasion, and resistance to anticancer therapy." (PMID 38398101, 2024). "Third, we investigated the effect of EREG on tumor development by using only several HCC lines with different levels of EGFR expression." (PMID 38673992, 2024). "Accordingly, higher EREG and AREG expression are associated with low CpG island methylator phenotype (CIMP) status as well as WT KRAS/BRAF, left-primary tumor location (PTL), and microsatellite stability (MSS) versus microsatellite instability (MSI)." (PMID 40727266, 2024). "High epiregulin levels were observed in SACC patients with large tumor sizes (≥4 cm) and higher clinical stages (stage III/IV)." (PMID 39409917, 2024).
tumor (continued). "We found that ISCA1 RNA was positively correlated with all six tumor stemness features in TGCTs and was positively correlated with DMPs, DNAss, ENHss, and EREG.METH in PCPGs but was negatively correlated with BLCA and BRCA." (PMID 39766805, 2024). "Anti-EREG antibodies significantly reduced the cell proliferation of Huh7 by LPS stimulation, suggesting that EREG plays a crucial role in LPS-induced tumor development." (PMID 38673992, 2024). "Most normal tissues show low levels of EREG expression, but the levels are elevated in different cancer types and promote tumor progression by activating EGFR signaling." (PMID 38334792, 2024). "We confirmed that activated HSCs stimulated with LPS expressed a high EREG expression in tumor tissue." (PMID 38673992, 2024). "Although epiregulin-enriched exosomes play a pivotal role in metastasis by affecting both tumor and lung endothelial cells, they can be potential therapeutic targets for controlling lung metastasis in patients with SACC." (PMID 39409917, 2024). "The EREG/AREG-EGFR communications serve as a pivotal factor in tumor proliferation and migration in several solid human cancers." (PMID 38600248, 2024). "The data suggest an accordance of high EREG expression and tumor recurrence, metastasis, increased PCa grading and PCa-related death." (PMID 36994208, 2023). "Autocrine stimulation of EGFR by AREG and EREG is a mechanism of tumor EGFR pathway dependence, so the impact of their expression on the response to EFGR-targeted therapy in mCRC patients has also received much attention." (PMID 37974093, 2023). "The EREG–EGFR axis participates in tumor progression by regulating several biological functions, including cell survival, proliferation, migration, and angiogenesis." (PMID 37020674, 2023). "EREG also promotes tumorigenicity, metastasis, drug resistance and cell plasticity and modulates the tumor microenvironment and metabolism." (PMID 36899869, 2023). "EREG expression seems to correlate with tumor recurrence, metastasis and increased grading of PCa patient samples." (PMID 36994208, 2023). "In summary, these findings suggest that CYP4A22-AS1 exhibit tumor-promoting effects through down-regulated miR-205-5p and miR-34c-5p targeting EREG and BCL-2 in vitro and in vivo." (PMID 37670265, 2023). "Toll-like receptors also induce tumor proliferation mediated by mitogens such as hepatocyte growth factors, amphiregulin and epiregulin." (PMID 38138294, 2023). "Gene expression profiling interactive analysis based on tumor and normal samples archived in the TCGA and the GTEx databases suggested a preferentially higher expression of EREG in human tumor specimens than their normal tissue controls for most cancer types." (PMID 36202915, 2022). "Conversely, EREG knockdown from PSC27EREG cells prior to tumor implantation considerably decreased tumor volumes." (PMID 36202915, 2022). "Epiregulin (EREG) a member of the Epithelial Growth Factor (EGF) family promotes tumor development, migration and invasion." (PMID 35844493, 2022). "Overall, the data establish EREG as both a tumor-promoting factor that is targetable to avert disease exacerbation and a circulating biomarker exploitable to monitor the host response to therapeutic agents in cancer clinics." (PMID 36202915, 2022). "The EREG protein level was increased in GC tissues and correlated with the tumor-node-metastasis stage and shorter overall survival (OS)." (PMID 34884633, 2021). "Future longitudinal studies should examine the potential carcinogenic characteristics of environmental contaminants to understand the implications of EREG-mediated tumor initiation." (PMID 34884633, 2021). "Except for tumor tissues, EREG was also found to be highly expressed in PDAC cell lines compared with HPNE cells, which are derived from normal human pancreatic duct." (PMID 33748108, 2021). "The EREG protein level in CRC tissues was significantly associated with invasion and distant tumor metastasis." (PMID 34884633, 2021).
tumor (continued). "Novel strategies targeting EREG/EGFR, tumor-associated macrophages, and alternative activation oncoproteins are under development or undergoing clinical trials." (PMID 34884633, 2021). "Regarding miR-186-3p, only one study has identified that it suppresses tumor growth and regulates glycolysis by directly targeting epiregulin in estrogen receptor-positive breast cancer cells." (PMID 34551673, 2021). "EREG proteins were significantly overexpressed in lung adenocarcinomas and correlated with aggressive tumor phenotypes." (PMID 34884633, 2021). "Understanding the specific role of crucial molecules such as EREG expression in cancer cells or tumor infiltrating immune cells can help in the development of targeted therapies for different tumors." (PMID 34884633, 2021). "As for miR-186-3p, only one study has identified that miR-186-3p suppresses tumor growth and regulates glycolysis by directly targeting epiregulin in estrogen receptor-positive breast cancer." (PMID 34551673, 2021). "At 20 weeks, tumor development was also significantly decreased in the EREG knockout (EREG−/−) mice when compared with wild-type control." (PMID 34884633, 2021). "In this study, we systematically assessed the prognostic performance of DNA replication-related genes for predicting tumor recurrence and constructed a novel and robust signature including EREG, KCTD13, MCM3AP, MCM3, POLD2, TERF2, and TP73." (PMID 33748108, 2021). "Understanding how specific tumor-promoting factors such as EREG are regulated under different cellular contexts and how oncogenic mutations confer alternative signal activation can help clinicians improve treatments, such as anti-EGFR therapy." (PMID 34884633, 2021). "Correlations between EREG mRNA levels at W6 with tumor regression or vascular parameters were also examined." (PMID 32674321, 2020). "The AUCs for AREG and EREG were 0.911 and 0.858, respectively, indicating their strong relationship with the tumor subgroup." (PMID 31181806, 2019). "In a xenograft tumor model, EREG expression in fibroblasts had a tumor-supportive function in an EREG-related pattern." (PMID 31234944, 2019). "EREG is essential for the NF-CAF transformation needed to induce EMT of tumor cells in a JAK2-STAT3- and IL-6-dependent manner in OSCC." (PMID 31234944, 2019). "In a recent work, EREG and AREG expression has been found to have a strong inverse correlation with methylation and to be inversely associated with right-sided tumor location, CIMP-H status and BRAF mutation." (PMID 34532592, 2018). "It was shown that the expression of EREG and HOXB9 is significantly increased in tumor tissues compared with healthy tissues (P < 0.01 for EREG, P < 0.001 for HOXB9)." (PMID 29199273, 2017). "In fact, the expression of AREG and EREG is coordinately regulated, and plays an important role in tumor growth and survival by generating an autocrine loop through EGFR." (PMID 28002810, 2017). "The cardinal role of EREG signaling is promotion of cell survival, which contributes to increased tumor volume." (PMID 27995036, 2016). "Tissue and pretreatment serum levels of AREG and EREG protein were negatively correlated with clinicopathological characteristics, such as depth of tumor invasion, distant metastases, and nerve invasion." (PMID 27344184, 2016). "Another study demonstrated that the anti-EREG antibody (epiregulin, epidermal growth factor family) is efficacious against tumor metastasis." (PMID 25685060, 2015). "We demonstrate that EREG signaling promotes cell survival, which contributes to increased tumor volume in vivo." (PMID 26215578, 2015).